PARP4 (poly(ADP-ribose) polymerase family member 4)
Diseases named in the same sentence as PARP4 in open-access papers (continued):
Sharing a sentence is not in itself a finding about the gene and the disease.
cancer (19 papers, 2013 to 2024). A tumor composed of atypical neoplastic, often pleomorphic cells that invade other tissues. "Having demonstrated hnRNPM as a prospective new association partner of PARP4, we sought to examine the underlying mechanisms by which it exerts its effects in cancer." (PMID 39034402, 2024). "A few studies also reported germline PARP4 mutations in cancer patients, and PARP4 was proposed as a candidate cancer susceptibility gene." (PMID 39034402, 2024). "Quite strikingly, we noted that the recurrent PARP4 I1039T mutation observed in the Asian LUAD cohort was also seen in other cancer cohorts at low frequencies." (PMID 39034402, 2024). "In relation to cancer, a study found that two PARP4 mutations were found in 43% of their cohort diagnosed with breast and thyroid cancer." (PMID 35096828, 2021). "There are no further reports about the relationship between these detected mutations and cancer except PARP4(c.3509C > T, p.Thr1170Ile)." (PMID 34923986, 2021). "To assess the consequence of the I1039T mutation in cancer, we compared the in vivo tumor-forming ability of iSAEC-K cells overexpressing either PARP4I1039T or PARP4WT in a clonal PARP4 knockout background." (PMID 39034402, 2024). "In our study, those genes (except for PARP4) were predominantly hypomethylated in carcinomas compared to the BOT groups (GR file)." (PMID 39456618, 2024). "Several PARP inhibitors have already been approved for cancer treatment and, in light of our results and those of previous reports, PARP4 emerges as a candidate actionable target for platinum‐resistant HGSOC." (PMID 33811746, 2021). "This review explores the functions of PARP4,6-16 and discusses the current knowledge of the potential roles these proteins may play in DNA damage repair and as targets for cancer therapeutics." (PMID 35096828, 2021). "Increased PARP-4 expression in some drug resistant cell lines has led to speculation that PARP-4 is involved in drug resistance in cancer, possibly through its role in vault particles." (PMID 33546365, 2021). "However, the results of functional analyses do not support the role of PARP4 as a susceptibility gene, emphasizing the importance of functional analysis for verifying candidate cancer susceptibility genes." (PMID 34976832, 2021). "In this review, we summarize the role and regulatory mechanism of PARP3, PARP4, and PARP6–16 in cancer." (PMID 34976832, 2021). "The absence of PARP4, or the downregulation of its coding gene, is related to cancer." (PMID 32325999, 2020). "Unlike PARP4, MVP expression levels had no significant impact on overall patient survival, indicating a surprising and unanticipated vault-independent function of PARP4 in cancer." (PMID 39034402, 2024).
tumor (15 papers, 2020 to 2025). "Binds hnRNPM to suppress LUAD tumorigenicity; PARP4 deficiency causes splicing dysregulation → promotes tumor progression." (PMID 40904702, 2025). "Using the largest Asian LUAD patient dataset as a starting point, we have identified PARP4 copy number loss or mutation at relatively high frequency, which we subsequently validated in vitro and in vivo as an important modulator of tumor progression." (PMID 39034402, 2024). "The splicing regulator hnRNPM is a potentially novel PARP4 interaction partner, the loss of which likewise promotes tumor formation." (PMID 39034402, 2024). "Other studies along the same lines consider PARP4 to be a breast cancer susceptibility gene; however, its function in this type of tumor is currently unknown." (PMID 41463260, 2025). "However, both SPTAN1 and APC, which were significantly associated with response, and PARP4, which was mutated in chemosensitive tumours only, have been described as DDR-involved genes." (PMID 34934968, 2021). "In a panel of patient-derived lung normal and tumor cell lines that we established, PARP4 protein levels were indeed lower in tumor cell lines, further supporting PARP4’s putative tumor suppressive function." (PMID 39034402, 2024). "To assess if PARP-hnRNPM interaction is essential for the tumor suppressive function of PARP4, we overexpressed PARP4 fragments in PARP4 clonal knockout A549 cells." (PMID 39034402, 2024). "Given the established role of PARP4 as a key subunit within the vault complex, we proceeded to determine if the vault complex is responsible for tumor-suppression." (PMID 39034402, 2024). "It would be interesting to further examine the relative contributions of PARP4 protein regions and integration with its enzymatic activity to PARP4’s tumor suppressive function." (PMID 39034402, 2024). "The observations underscored the broader relevance of PARP4’s tumor suppressive activity beyond our genetically-defined iSAEC-K cellular model." (PMID 39034402, 2024). "Although several of the clinically approved PARP inhibitors also target PARP4, in addition to PARP1-3, it is unclear what the effect of inhibiting PARP4 would have on tumour cells." (PMID 35096828, 2021). "Survival analysis shows that low expression of PARP4 is correlated with poor progression-free survival (PFS) and overall survival (OS), suggesting that PARP4 functions as a tumor suppressor in BC." (PMID 34976832, 2021). "Tumor volume and weight in groups sh-PARP4-1 and sh-PARP4-2 were comparable to sh-PARP4-NC." (PMID 39885134, 2025). "KU55933 monotherapy delayed tumor growth in the sh-PARP4-NC group." (PMID 39885134, 2025). "Researchers have identified a significant, vault‐independent, tumor‐suppressive role of PARP4." (PMID 40904702, 2025). "Interestingly, PARP4-Fragment 1-expressing cells also had significantly reduced soft agar colony forming ability, indicating the contribution of PARP4-Fragment 1 to PARP4’s tumor suppressive functionality, possibly through its ADP-ribosylation activity." (PMID 39034402, 2024). "Disruption of the vault complex, with which PARP4 is commonly associated, did not alter tumorigenicity, indicating that PARP4’s tumor suppressive activity is mediated independently." (PMID 39034402, 2024). "Notably, genes, such as DDX11 (12p11.21), IGLV2-18 (22q11.22), OR8G5 (11q24.2), PARP4 (13q12.12), USP10 (16q24.1), and ZNF208 (19p12), exhibited multiple mutations and demonstrated tumor-driving effects." (PMID 39711964, 2024). "Here, we provide the first evidence of a vault-independent tumor suppressive role for PARP4." (PMID 39034402, 2024). "Notably, PARP4, PARP7, PARP10, PARP11, and PARP15 have been clearly implicated in tumor development and progression, functioning either as oncoproteins with prognostic relevance or, in certain contexts, as tumor-suppressive factors." (PMID 41463260, 2025). "In contrast, tumor growth inhibition by KU55933 was more significant within the sh-PARP4-1 and sh-PARP4-2 groups." (PMID 39885134, 2025).
tumor (continued). "Compared to wild-type PARP4, the PARP domain deletion resulted in larger tumors, signifying the importance of the PARP domain to PARP4’s tumor suppressive activity." (PMID 39034402, 2024). "Moreover, early research indicated that PARP4-deficient mice had no obvious developmental defect, and subsequent work declared that PARP4-deficient mice were prone to carcinogen-induced tumors, suggesting that PARP4 may function as a tumor suppressor." (PMID 36035988, 2022). "Given the importance of vault particles in RNA transport, PARP4 must be considered a regulator of the immune response during embryonic development, detoxification of toxins in adult brains, being shared with PARP6, and resistance of tumor cells to different drugs." (PMID 41463260, 2025). "We thus examined the involvement of PARP4’s ADP-ribosylation catalytic activity in its tumor suppressive function by overexpressing mutant PARP4 lacking its PARP catalytic domain in PARP4 clonal knockout iSAEC-K cells, which were used in subsequent in vivo tumorigenicity assays." (PMID 39034402, 2024). "This indicated that the knockdown of PARP4 alone could not inhibit tumor progression." (PMID 39885134, 2025). "Furthermore, APC (p < 0.0001), ASXL1 (p < 0.0001), DNMT3B (p = 0.001), PARP4 (p = 0.002), MET (p = 0.01), TOP1 (p = 0.01), KDR (p = 0.01), SRC (p = 0.01), PAK1 (p = 0.015), ALK (p = 0.02), and MYC (p = 0.03) alterations were found to be more common in tumor samples from AO mCRC patients." (PMID 33194656, 2020).
metabolic disorders (1 paper, 2022). "Furthermore, the effect of PARP4 and ERCC1 variations on the relation between PMs exposure and glucose level has not yet been reported, although positive associations between DNA damage accumulation and the development of metabolic disorders were reported." (PMID 35627777, 2022).
PARP4 also shares sentences with these, for which no sentence is quoted: bone osteosarcoma (1 paper); colorectal cancer (1); head and neck cancer (1); hepatocellular carcinoma (1); Liver Abnormality (1); renal carcinoma (1); scleroderma (1); stomach cancer (1); thyroid (1).